BRD4 (bromodomain containing 4)
Diseases named in the same sentence as BRD4 in open-access papers (continued):
Sharing a sentence is not in itself a finding about the gene and the disease.
colorectal cancer (continued). "For example, in colorectal cancer, the loss of the BAF chromatin remodeler subunit ARID1A, a tumor suppressor, leads to the derepression of a specific set of HERVH loci, which in turn modulates BRD4-dependent transcription." (PMID 40618134, 2025). "The observed salutary effects of CDK4/6 inhibition on anti-tumor immunity could be the basis for a triple combination regimen associating a CDK4/6 inhibitor, an immune checkpoint inhibitor and a BRD4 inhibitor in colorectal cancer." (PMID 40699853, 2025). "Moreover, high expression of both ACE2 and BRD4 mRNAs compared with low ACE2 plus low BRD4 levels also predicted significantly reduced survival in colorectal cancer patients (p = 0.0174)." (PMID 36801948, 2023). "Precision oncology approaches might, in principle, target colorectal cancers in which high ACE2 plus high BRD4 expression is predictive of poor survival." (PMID 36801948, 2023). "In colorectal cancer, the expression of lncRNA CCAT1 (colon cancer–associated transcript 1) may potentially predict the response to JQ1, a chemical inhibitor of bromodomain containing four (BRD4) protein important for colorectal cancer proliferation." (PMID 37628760, 2023). "In addition, BRD4 has been shown to promote the proliferation of colorectal cancer cells, while the BRD4 inhibitor AZD5153 reversed this effect." (PMID 35164758, 2022). "Moreover, apoptosis of colorectal cancer cells induced by Brd4 knockdown or inhibition in combination with chemotherapeutic drugs, such as 5-fluorouracil (5-FU) or oxaliplatin, is markedly suppressed with DR5 genetic deletion." (PMID 36539410, 2022). "Using inhibitor AZD5153 to inhibit BRD4 can inhibit the proliferation of colorectal cancer cells." (PMID 35252219, 2021). "According to the literature, BRD4 might promote cell proliferation in pancreatic ductal adenocarcinoma, hepatocellular carcinoma, and colorectal cancer." (PMID 31621555, 2020). "Based on the indicated role of BRD4 in malignant disease, we analysed the expression of BRD4 in colorectal cancer patient using TCGA database, as showed in, compared with normal tissues, the level of BRD4 were significantly increased in colorectal cancer tissues (p<0.001)." (PMID 31523195, 2019). "Moreover, the chemo‐regulation effects of DdLD NPs could inhibit colorectal cancer glycolysis to reduce the lactate production, which downregulated PD‐L1 expression through BRD4 degradation." (PMID 38239040, 2024). "This suggested that targeting BRD4 might be a valuable strategy for colorectal cancer treatment." (PMID 31523195, 2019). "In studies on other types of cancer, such as in colorectal cancer and bladder cancer cell lines, BRD4-bound circRNA regulates MYC expression, and BRD4 bound the super-enhancer regulates expression levels of lncRNA PVT1 and MYC." (PMID 36895010, 2023). "CSCs from MC38 colorectal cancer and MC38-derived tumors showed that THF inhibited CSC formation and induced apoptosis of MC38-derived CSCs through the c-Myc/BRD4/PD-L1/RelB/IL6 axis." (PMID 37924094, 2023). "We examined the relationship between PD-L1 and CSC formation on MC38 colorectal cancer, MC38-derived tumor, and 4T1-derived tumor using THF, a natural compound of BRD4 inhibitor." (PMID 37924094, 2023). "Because in lung cancer cells BRD2 was considered “proviral” and positively regulated expression of the ACE2 receptor whereas BRD4 was “antiviral”8, these BET proteins were examined in colorectal cancer datasets." (PMID 36801948, 2023). "Mechanistically, exosomal circLPAR1 is up-taken by colorectal cancer cells and binds eIF3h, leading to decreased accumulation of BRD4 (bromodomain containing 4), to inhibition of cell proliferation and to invasiveness." (PMID 36831450, 2023). "Mechanistically, exosomal circLPAR1 is internalized by colorectal cancer cells and binds eIF3h to reduce METTL3-eIF3h-dependent mRNA translation, thereby inhibiting BRD4 expression and suppressing cellular proliferation, invasion, and migration." (PMID 35164758, 2022).
colorectal cancer (continued). "Regarding the mechanism involved in this, we also identified NUP210 as a BRD4-driven NUP and determinant of the nuclear architecture in colorectal cancer cells." (PMID 35159127, 2022). "The BRD4 expression plasmid elevated the decrease in BRD4 levels caused by circLPAR1 expression and promoted the acquisition of colorectal cancer cell phenotypes, whereas AZD5153 reversed the tumor-promoting effect of high BRD4 levels." (PMID 35164758, 2022). "In colorectal cancer cells, DR5 and Endoplasmic reticulum (ER) stress response genes, including C/EBP homologous protein (CHOP), are significantly induced in response to Brd4 depletion and BET inhibitors (BETi) treatment." (PMID 36539410, 2022). "Mechanistically, exosomal circLPAR1 expression level led to decreased BRD4 levels because it binds eIF3h and inhibits the METTL3–eIF3h interaction, which remarkably suppressed colorectal cancer development." (PMID 35164758, 2022). "CAF-secreted IL-6 and CXCL8 induce Bromodomain-containing protein 4 (BRD4) protein expression and lead to chromatin remodeling and Bromodomain and Extraterminal (BET) inhibitor resistance in colorectal cancer (CRC)." (PMID 35011369, 2021). "In our study, we reported that the BRD4 inhibitor, AZD5153, potently suppressed the proliferation and induced apoptosis of colorectal cancer cells in vitro and in vivo." (PMID 31523195, 2019). "In this article, we review the data about the expression of BRD4 in patients with inflammatory bowel diseases (IBDs) and patients with colorectal cancer (CRC) and discuss the more recent findings supporting the therapeutic benefit of BRD4 inhibitors in both IBD- and CRC-like mouse models." (PMID 41311847, 2025). "In this article, we review the data about the expression and role of BRD4 in patients with Crohn’s disease and patients with ulcerative colitis, the major human inflammatory bowel diseases (IBD), as well as in patients with colorectal cancer (CRC)." (PMID 41311847, 2025). "Importantly, in colorectal cancer, PRR7-AS1 expression was positively correlated with the expression of BRD4, the primary H3K27ac signal reader." (PMID 37091809, 2023). "AZD5153, a novel specific BRD4 inhibitor, showed potent anticancer effects in several cancer types, but its therapeutic potential has not been fully evaluated in colorectal cancer cells." (PMID 31523195, 2019). "However, the role of BRD4 has not been well studied for colorectal cancer, with the exception of one paper demonstrated that overexpression of BRD4 reduced colorectal tumor growth in vivo." (PMID 25603177, 2015). "Furthermore, we examined the expression of BRD4 in 9 human colorectal cancer cell lines(HCT116, LoVo, RKO, Caco2, HT29, SW48, SW480, SW620, and DLD1 cells) and normal colorectal epithelial cell FHC, which also indicated the same result that BRD4 was overexpressed in human colorectal cancer cells." (PMID 31523195, 2019).
gastric cancer (45 papers, 2016 to 2025). A primary or metastatic malignant neoplasm involving the stomach. "BRD4 promotes the progression and metastasis of gastric cancer, and the abundance of BRD4 in human gastric cancer tissue is associated with shorter survival in patients with non-metastatic gastric cancer." (PMID 36171897, 2022). "High mRNA expression of BRD4 was associated with poor overall survival of patients with gastric cancer." (PMID 34733788, 2021). "Whether BRD4 loss resulted from PRDM1 knockdown rendering stomach cancer insensitive toward IBET151 was of concern, so further testing found shPRDM1-SNU-1 displayed decreased sensitivity toward IBET151 while this inhibitor showed an obvious suppression on shLuc-SNU-1 in terms of proliferation." (PMID 38540967, 2024). "In gastric cancer, BRD4 triggers c-MYC activation, leading to enhanced cell proliferation and reduced apoptosis." (PMID 39430761, 2024). "Cell-line experimentation indeed validated that PRDM1 knockdown in human stomach cancer cell line SNU-1 decreased BRD4 expression, proliferation, and sensitivity to BET inhibitor." (PMID 38540967, 2024). "Hyperglycemia also enhances gastric carcinoma proliferation and migration via thr Pin1/BRD4 transcriptional pathway, involved in the hyperglycemia‐induced inflammatory process." (PMID 38751364, 2024). "Pan-cancer analysis revealed that both CDK4 and BRD4 are super essential genes (Gene Effect score < -1) for gastric cancer cells." (PMID 36755269, 2023). "Altogether, these results suggested that CDK4/6 inhibitors induce chromatin remodeling in gastric cancer cells characterized by the extensive enhancer activation and proposed that BRD4 was a promising combination target for ABE." (PMID 36755269, 2023). "DSC2 also inhibited the metastasis of gastric cancer by inhibiting the BRD4/Snail signaling pathway and the transcriptional activity of β-catenin." (PMID 36817446, 2023). "BRD4 phosphorylation at threonine (T) 204 induced gastric cancer cell proliferation, tumor formation, migration, and invasion, while BRD4-T204A mutation reversed this carcinogenesis." (PMID 37737256, 2023). "Collectively, these results suggest that the BRD4 inhibitor JQ1 augments the antitumor efficacy of ABE in preclinical models of gastric carcinoma via inducing cellular senescence." (PMID 36755269, 2023). "BRD4 has been reported to be able to promote the progression of gastric cancer by regulating c-MYC transcription and epigenetics." (PMID 34876902, 2021). "The messenger RNA (mRNA) expression of BRD4 in gastric cancer raised significantly than those in normal tissues, which suggested poor outcome of patients with gastric cancer." (PMID 34733788, 2021). "More recently, it has been shown that the inhibition of BRD4 activity by its selective inhibitors displays therapeutic potential for liver cancer, gastric cancer, pituitary adenoma, aeroallergen-induced inflammation, and airway remodeling." (PMID 34336890, 2021). "And in gastric cancer, bromodomain-containing protein 4 (BRD4) recognized acetylated SNAI1 and prevented its interaction with E3 ligase FBXL14 and β-Trcp1, further decreased its polyubiquitination and proteasomal degradation." (PMID 34718323, 2021). "BRD4 recognizes acetylated K146 and K187 on Snail1 to prevent it from being degraded by E3 ligases in gastric cancer." (PMID 34917071, 2021). "From spheroid gastric cancer cells, miR-216a-3p has also been identified to be downregulated by BRD4." (PMID 33562727, 2021). "Western blotting analysis illustrated that ARV-825 displayed efficient degradation of BRD4 in four gastric cancer cells." (PMID 34733788, 2021). "BRD4 is overexpressed within spheroid gastric cancer cells, and downregulates the expression of miR-216a-3p by methylating its promoter region." (PMID 33562727, 2021). "Prolyl isomerase PIN1 regulates the stability and transcriptional activity and oncogenic potential of BRD4 in gastric cancer cells." (PMID 34540900, 2021).
gastric cancer (continued). "For example, BRD4 stabilizes the progression of stomach cancer through Snail and promotes the stemness of gastric cancer cells by inhibiting Wnt/β-catenin signal transduction." (PMID 35252219, 2021). "BRD4 was shown to be essential for maintaining stemness characteristics in gastric cancer and embryonic stem cells." (PMID 32826850, 2020). "In human gastric cancer cells PIN1 induces a conformational change of phosphorylated BRD4 supporting its interaction with CDK9, thus improving BRD4-mediated gene expression relevant for gastric cancer cell proliferation and tumor development." (PMID 30873382, 2019). "All together, our studies have explored the anti-proliferative effect of JQ1 in gastric cancer cells and also identified BRD4-dependent regulation of cellular senescence via E2F/miRNA-106b-5p/p21 axis as an underlying mechanism." (PMID 29434197, 2018). "Since BRD4 often serves as a positive transcription regulator, we suspected that BRD4-regulated miRNAs would have enhanced expression in gastric cancer cells." (PMID 29434197, 2018). "Taken together, these results demonstrate that BRD4 regulates gastric cancer cell proliferation via cellular senescence." (PMID 29434197, 2018). "In the present study, we identified chromatin remodeling-related PRDM1 as a contributor to stomach cancer formation via modulations on cell proliferation and BRD4 expression; specifically, via systematic bioinformatic analysis on the chromatin remodeling-related gene list suggested by our team." (PMID 38540967, 2024). "Applying databases of cBioPortal and CCLE for proper in vitro validation, we found human stomach cancer cell lines tended to have greater BRD4 expressions once their PRDM1 expressions were higher, with this association also being observed in the TCGA STAD dataset." (PMID 38540967, 2024). "Importantly, JQ1 is thought to mitigate the proliferation of gastric cancer cells by inhibiting BRD4 and the E2F/miR-106b-5p/p21 axis and thus inducing senescence." (PMID 39125612, 2024). "BRD4 was screened out in more than 50% of gastric cancer cell lines (19/35)." (PMID 36755269, 2023). "It is reported that BRD4 promote progression and metastasis of gastric cancer." (PMID 35601153, 2022). "High expression of BRD4 indicated poor prognosis in patients with gastric cancer." (PMID 34733788, 2021). "ARV-825, a BRD4 inhibitor, could effectively suppress the growth and elevate the apoptosis of gastric cancer cells via transcription downregulation of c-MYC and PLK1." (PMID 34733788, 2021). "High mRNA expression of BRD4 in gastric cancer indicated poor prognosis." (PMID 34733788, 2021). "Moreover, Pin1 enhances the stability of BRD4 by inhibiting its ubiquitination and increasing transcriptional activity of BRD4 to promote the proliferation of gastric cancer." (PMID 32296699, 2020). "Since miRNAs often have multiple targets, it is possible that BRD4-mediated miR-106b-5p might have additional functions in gastric cancer cells." (PMID 29434197, 2018). "BRD4 is overexpressed in different cancers, including gastric cancer 26,35,36." (PMID 29434197, 2018). "In addition, we demonstrated a BRD4-dependent regulatory pathway via E2F/miR-106b/p21 axis for cellular senescence in gastric cancer cells." (PMID 29434197, 2018). "Finally, we demonstrated that inhibition of E2F suppressed the binding of BRD4 to the promoter of miR-106b-5p and inhibited its transcription, leading to the increased p21 levels and cellular senescence in gastric cancer cells." (PMID 29434197, 2018). "It would be interesting to determine whether miR-106b-5p accounts for the tumor-promoting activity of BRD4 in gastric cancer and other cancers." (PMID 29434197, 2018).
gastric cancer (continued). "Statistical analysis reveals that BRD4 is highly overexpressed in gastric cancer tissues, suggesting that BRD4 might contribute to the proliferation of gastric cancer cells." (PMID 29434197, 2018). "In the metastatic lymph node from a gastric cancer HGC-27 cell line, MAGI2-AS3 overexpression might be caused by the transcriptional regulator bromodomain containing 4 (BRD4) and its interaction with histone H3 acetylated at lysine 27, enriched in the promoter region MAGI2-AS3." (PMID 34503076, 2021). "In a mouse model of orthotopic gastric cancer, M@BP can effectively target and accumulate in gastric cancer cells, blocking the activation of CDK9 and BRD4 and impeding the growth of gastric cancer cells." (PMID 40190709, 2025). "Following bioinformatic analysis, we performed cell-line experiments to confirm the effects of PRDM1 on proliferation, BRD4 expression, and response to IBET151 in stomach cancer." (PMID 38540967, 2024). "BRD4 activates c-MYC through transcriptional and epigenetic regulatory mechanisms, thereby increasing the proliferation of gastric cancer cells and inhibiting apoptosis." (PMID 39430761, 2024). "In gastric cancer DTP cells, we found that an increase in H3K27ac and BRD4, acetylated histone-dependent modifiers, was critical for the expression of ALDH1A3, a DTP survival factor." (PMID 38669046, 2024). "BRD4, a well-established reader for H3K27ac reported to promote gastric cancer progression and metastasis, was elevated in gastric tumors and was correlated to inferior prognoses of GC patients." (PMID 36755269, 2023). "BRD4 activates C-MYC through transcriptional and epigenetic regulation, which increases the proliferation of gastric cancer cells and inhibits the apoptosis of gastric cancer cells." (PMID 37735667, 2023). "Inhibition of BRD4 limits the communication between super-enhancers and promoters for oncogene transcription and inhibition of BRD4 has shown to downregulate Snail affecting EMT and metastatic potential of breast and gastric cancers." (PMID 36333293, 2022). "Our previous research has shown that AZD5153, a novel BRD4 inhibitor, downregulates MUS81 expression, and reduces the migration of gastric cancer cells in vitro and in vivo." (PMID 35480096, 2022). "BRD4, a member of the bromodomain and extraterminal (BET) family, is elevated in multiple cancer tissues, including gastric cancer (GC)." (PMID 36352160, 2022). "PIN1 also catalyzes the isomerization of BRD4 Pro205 and induces its conformation change to promote CDK9 interaction and transcriptional activity and gastric cancer cell proliferation." (PMID 34540900, 2021). "The findings demonstrated that inhibiting BRD4 by ARV-825 led to an expression reduction in MYC and PLK1 at mRNA and protein levels in gastric cancer cells." (PMID 34733788, 2021). "ARV-825 induced degradation of BRD4, BRD2, BRD3, c-MYC, and polo-like kinase 1 (PLK1) proteins in four gastric cancer cell lines." (PMID 34733788, 2021). "Particularly, BRD4 identifies acetylated K146 and K187 on Snail1 in an acetylation-dependent manner to prevent its degradation by FBXL14 and β-TrCP1 in gastric cancer." (PMID 34917071, 2021). "The IC50 values of other BRD4 inhibitors, such as OTX015 and JQ1, were compared with that of ARV-825 in gastric cancer cells." (PMID 34733788, 2021). "In this study, ARV-825 in gastric cancer had lower IC50 than that of JQ1 and OTX015, more thorough degradation of BRD4 and less toxicity and side effects in vivo." (PMID 34733788, 2021). "ARV-825 in gastric cancer had lower IC50, more thorough degradation of BRD4, and less toxicity and side effects in vivo." (PMID 34733788, 2021). "In gastric cancer cell lines, BRD4 inhibition did not alter RUNX2 expression itself, however BRD4 was required for maintenance of open chromatin at RUNX2 binding sites in the genome." (PMID 38063851, 2024).
gastric cancer (continued). "BRD4 binds with Snail on acetylated lysine K146 and K187 to inhibit Snail degradation by its E3 ubiquitin ligases FBXL14 and β-TrCP1, thereby maintaining progression and metastasis in gastric cancer." (PMID 37737256, 2023). "BRD4, the H3K27ac signal reader, was positively relevant with CCT3 expression in gastric cancer." (PMID 36313331, 2022). "BRD4, BRD2, and BRD3 were abundantly expressed in MGC803, HGC27, AGS, SGC7901, BGC823, and SNU-216 cells, implying that the BET proteins were diffusely expressed in gastric cancer cells." (PMID 34733788, 2021). "Depletion of BRD4, which was overexpressed in gastric cancer tissues, but not other BET proteins recapitulated JQ1-induced cellular senescence with increased cellular SA-β-Gal activity and elevated p21 levels." (PMID 29434197, 2018). "However, our own data indicate that ACP-02, which has the highest BRD4 and c-MYC levels are less sensitive to BET inhibition and there seems to be little correlation between BRD4 levels and MYC regulation and antiproliferative effect in the Asian gastric cancer cell lines." (PMID 27259267, 2016).